RN7SL822P (RNA, 7SL, cytoplasmic 822, pseudogene)
Gene: Miscellaneous RNA gene on chromosome 4 (55,215,624 to 55,215,919, reverse strand). Ensembl gene ENSG00000239545.
Homologues: Orthologues: chimpanzee Metazoa_SRP (99% identical), macaque Metazoa_SRP (87% identical). Paralogues in human: RN7SL1 (85% identical), RN7SL2 (85% identical), RN7SL3 (83% identical), RN7SL769P (82% identical), RN7SL543P (81% identical), RN7SL296P (81% identical), RN7SL444P (81% identical), RN7SL300P (80% identical), RN7SL45P (80% identical), RN7SL478P (80% identical), RN7SL44P (80% identical), RN7SL566P (80% identical), and 706 more.